RAD51 (RAD51 recombinase)
Diseases named in the same sentence as RAD51 in open-access papers (continued):
Sharing a sentence is not in itself a finding about the gene and the disease.
osteosarcoma (25 papers, 2011 to 2025). A usually aggressive malignant bone-forming mesenchymal neoplasm, predominantly affecting adolescents and young adults. "β-Thujaplicin, a natural monoterpenoid found in the wood of trees in the Cupressaceae family, sensitized osteosarcoma cells to damage caused by ionizing radiation, as it inhibits the formation of RAD51 foci and keeps RPA phosphorylated." (PMID 33330091, 2020). "In osteosarcoma, suppression of Rad51, the key protein of DNA homologous recombination repair, correlated with cell cycle arrest and limited in vivo tumor growth, while also sensitizing osteosarcoma HOS cells to ionizing radiation and chemotherapy." (PMID 36232719, 2022). "The cell cycle of the U-2 OS osteosarcoma cell line was analyzed as a cancer cell example to observe the change of RAD51 expressed during the cell cycle." (PMID 35359409, 2022). "We established miR-34b-3p overexpressing and miR-34b-3p/RAD51 cooverexpressing osteosarcoma cells to evaluate the involvement of RAD51." (PMID 34456631, 2021). "RAD51 regulated the cell cycle and DNA damage checkpoint, and these pathways were significantly upregulated in our clinical osteosarcoma tissue samples." (PMID 34456631, 2021). "We therefore quantified RAD51 recruitment in RB1-defective osteosarcoma lines using ionising radiation (IR) to induce DDSBs." (PMID 34862364, 2021). "CCK-8 assay results showed that miR-34b-3p overexpression inhibited cell proliferation as compared to the control group, whereas miR-34b-3p/RAD51 cooverexpression recovered the proliferation of osteosarcoma cells." (PMID 34456631, 2021). "RAD51 is readily detected on chromatin as nuclear foci in human osteosarcoma U2OS cells even during unperturbed replication." (PMID 32669601, 2020). "For example, suberoylanilide hydroxamic acid has been demonstrated to downregulate the expression of DNA repair Rad51 protein in cancers such as osteosarcoma and rhabdomyosarcoma." (PMID 28829799, 2017). "miR-103 and miR-107 target Rad51 and inhibit formation of Rad51 foci in response to DNA damage in osteosarcoma cells and subsequently increase sensitivity to Olaparib." (PMID 27642590, 2016). "Two previous attempts to map the minimal Rad51 promoter, both performed in the U2-OS osteosarcoma cell line, identified different essential promoter domains: −204/−58 and −536/−412." (PMID 22174876, 2011). "Evidence shows that targeting RAD51 contributes to overcome the radioresistance of some kinds of cancers, such as methotrexate inhibiting RAD51 expression and radiosensitizing human osteosarcoma cells." (PMID 37108815, 2023). "Therefore, positively regulated RAD51 promoted proliferation and inhibited apoptosis of osteosarcoma cells." (PMID 34456631, 2021). "RS-1 enhances HDR in HEK-293A and U2OS osteosarcoma cell lines by recruiting RAD51." (PMID 34503562, 2021). "Given that CHO cells deficient for RAD51C, RAD51D, XRCC2 or XRCC3, and human HCT116 cells deficient for XRCC3 are viable, we attempted to disrupt each classical RAD51 paralog individually in transformed human osteosarcoma U2OS and human embryonic kidney HEK293 cells." (PMID 31584931, 2019). "Similarly, overexpression of miR-96 in osteosarcoma U2OS cells reduced the levels of Rad51 by directly targeting its coding region, decreasing the efficiency of HR and enhancing sensitivity to Olaparib." (PMID 27642590, 2016). "In a similar fashion, miR-103 and miR-107, when overexpressed, reduced HRR and sensitized osteosarcoma cells to various DNA-damaging agents, including cisplatin and a PARP inhibitor by targeting RAD51." (PMID 35328651, 2022). "Overexpression of miR-96 decreased the efficiency of HRR and enhanced the sensitivity of osteosarcoma cells to the PARP inhibitor, AZD2281, and cisplatin, indicating that miR-96 regulates DNA repair and chemosensitivity by repressing RAD51." (PMID 35328651, 2022).
osteosarcoma (continued). "We observed a significant DNA damage-dependent RAD51 recruitment, evidenced by increased numbers of cells with >15 RAD51 foci, and a significant increase in foci numbers per cell in all RB1-defective osteosarcoma lines except one, LM7." (PMID 34862364, 2021). "Overexpressing HCG9 promoted RAD51 expression and suppressed H2A.X expression, indicating HCG9 induced mitosis and hyperproliferation of the osteosarcoma cells." (PMID 34456631, 2021). "Our data also explain why a BRCA2-derived peptide that targets RAD51 function elicited olaparib-induced cell death of U2OS human osteosarcoma cells but not of noncancerous cell lines." (PMID 35969531, 2022). "Commercial carriers such as RNAiFectTM reagent (Qiagen), LipofectamineTM 2000 and OligofectamineTM(Invitrogen) were used to deliver CDC20, RAD51, and CHEK1 siRNA, respectively, and these studies were conducted in pancreatic, non-small-cell lung carcinoma (NSCLC), and osteosarcoma cell-lines." (PMID 25763370, 2015). "In addition, knockdown of RAD51 expression reversed drug resistance to gemcitabine in human non-SCLC cells and induced radio- and chemosensitivity in osteosarcoma cells." (PMID 37798649, 2023).
non-small cell lung carcinoma (23 papers, 2005 to 2025). A group of at least three distinct histological types of lung cancer, including non-small cell squamous cell carcinoma, adenocarcinoma, and large cell carcinoma. "In the mechanism of action regarding the reversal of mitomycin C (MMC)-induced cytotoxicity in non-small-cell lung cancer (NSCLC) cells (A549 and H1703), astaxanthin was linked to the inhibition of the expression of Rad51 and phospho-AKT (Ser473) protein." (PMID 38667770, 2024). "It was reported that RAD51 expression increases after irradiation on non-small cell lung cancer cell lines H820 and A549 and on esophageal squamous cell carcinoma cell lines KYSE30 and KYS450." (PMID 37798649, 2023). "On the contrary, one study reported that inducing autophagy reduces RAD51 expression in non-small cell lung cancer (NSCLC) cell models." (PMID 34067336, 2021). "In human non-small-cell lung cancer cells, RAD51 mRNA expression can be induced by gemcitabine-mediated activation of ERK1/225." (PMID 32719412, 2020). "AKT1 is a regulatory component in the homologous recombination repair of DNA-DSB in a Rad51-dependent manner in non-small cell lung cancer cells." (PMID 32711558, 2020). "A previous study from our laboratory showed that AKT1-siRNA knockdown in the non-small cell lung cancer cell line A549 significantly reduced both Rad51 protein levels and foci formation." (PMID 31847370, 2019). "This study was aimed to evaluate Rad51 expression to serve as prognostic marker in non-small-cell lung cancer (NSCLC)." (PMID 15956972, 2005). "As an example, in early- to mid-stage non-small cell lung cancer, Claspin was only one of a set of five genes (POLQ, PLK1, RAD51, CDC6, and CLSPN) encoding proteins involved in the maintenance of genome stability that were found to be consistently upregulated and associated with poor survival." (PMID 41009395, 2025). "In terms of targeting DSB repair, it has been shown that DNA-PKcs inhibition (NU7026) in combination with X-ray irradiation or CIRT (50 keV/μm) in non-small cell lung cancer (H1299) cells was more effective compared with inhibiting the HR pathway (using the Rad51 inhibitor, B02)." (PMID 37695845, 2023). "Supporting this, a study has combined the use of olaparib and B02 (a potent Rad51 inhibitor), to show radiosensitisation of non-small cell lung cancer (A549) and pancreatic cancer (KP4 and PANC1) cells to both low-LET photons and relatively high LET protons (1.3 keV; 25 keV/μm)." (PMID 37695845, 2023). "Jen-Chung Ko reported that gefitinib could decrease Rad51 stability by promoting 26s proteasome-dependent degradation in human non-small cell lung cancer cells." (PMID 26752698, 2016). "We tested this prediction by monitoring RAD51 foci formation after the exposure of A549 non-small cell lung carcinoma (NSCLC) cells to ionizing radiation (IR), using a robust cell-based assay based on high-content microscopy with the Cellomics ArrayScan VTI, to objectively enumerate RAD51 foci." (PMID 33662256, 2021). "In addition, over-expression of POLQ, PLK1, RAD51, CDC6, and CLSPN was found to correlate with worse prognosis in non-small cell lung cancer." (PMID 41009395, 2025).
gastric cancer (17 papers, 2014 to 2025). A primary or metastatic malignant neoplasm involving the stomach. "High HRD gastric cancer cell lines demonstrated functional HR deficiency by RAD51 foci assay and increased sensitivity to platinum chemotherapy and PARP inhibitors." (PMID 38589664, 2024). "In our previous study, we evaluated the host RAD51 G135C polymorphism as the important predictor for the gastric cancer in H. pylori infected patients in Bhutan." (PMID 29107979, 2017). "Analyzing 121 advanced gastric cancer surgical specimens, the authors found that loss of nuclear RADiation sensitive 51 (RAD51) expression was associated with more aggressive tumor features such as vascular invasion, lymph node metastasis, and larger tumor size." (PMID 40869030, 2025). "Such discrepancies point toward post-transcriptional or post-translational regulation mechanisms impacting RAD51 activity in gastric cancer." (PMID 40869030, 2025). "FBXO5 can block CRIP1-promoted homologous recombination repair by preventing nuclear enrichment of RAD51, thereby restoring chemotherapy sensitivity of gastric cancer cells with high CRIP1 expression." (PMID 35720327, 2022). "Another report showed that RAD51 knockdown synergizes with the effects of chemotherapy on gastric cancer, suggesting the importance of HRR in CSC." (PMID 35567502, 2022). "Studies also have shown that gastric cancer tissues have higher levels of RAD51 expression compared with normal tissues." (PMID 36035159, 2022). "As γH2AX represent unrepaired DNA damage while RAD51 indicate homologous recombination repair progression, these results suggested that Sophoridine induces G2/M phase arrest in gastric cancer cells via inhibiting DNA damage repair." (PMID 32571331, 2020). "Therefore, BRCA1 and RAD51 can be used as biomarkers for the clinical diagnosis of gastric cancer to evaluate the prognostic effect of the disease." (PMID 36035159, 2022). "This suggests that RAD51 G135C may be an important predictor for gastric cancer of Helicobacter pylori-infected patients." (PMID 31186630, 2019). "Additionally, reduced levels of Rad51 expression by siRNA are shown to increase sensitivity to PARPi in human gastric cancer cells, and restoration of Rad51 via plasmid transfection attenuated drug sensitivity." (PMID 29340034, 2017). "Next, to test whether gastric cancer cell lines with high HRD scores are functionally HR deficient, we employed a RAD51 foci functional assay, which assesses HR proficiency by interrogating the ability of RAD51 foci to form in response to double strand DNA (dsDNA) breaks." (PMID 38589664, 2024).
gastric cancer (continued). "The results highlight that epigenetic mechanisms, particularly methylation of RAD51, BRCA1, and BRCA2 genes, are frequently involved in gastric cancer development and progression." (PMID 40869030, 2025). "Hp upregulated the expression of RING1/RAD51 by upregulating lncRNA SNHG17 as a ceRNA for miR-3909, changed the DNA repair system, and promoted the occurrence of gastric cancer." (PMID 34568091, 2021).
gastric cancer (continued). "It was shown that helicobacter pylori infection elevated SNHG17 expression in gastric cancers, resulting in increased genome instability via a SNHG17/miR-3909/RING1/Rad51 pathway." (PMID 34671012, 2021). "Moreover, RAD51 and BAX also exhibited negative correlations (Cor = -0.04, FDR = 0.41 for RAD51 and Cor = -0.09, FDR = 0.074 for BAX) with expression in gastric cancer." (PMID 40652278, 2025).